MTOR (mechanistic target of rapamycin kinase)
Diseases named in the same sentence as MTOR in open-access papers (continued):
Sharing a sentence is not in itself a finding about the gene and the disease.
breast cancer (continued). "The conducted study allowed us to compare the clinical and molecular features, such as age, lymph node metastasis, ER, PR, HER2 status, Ki-67 index and the histopathological malignancy level with the mutations and expressions of genes related to the PI3K/Akt/mTOR pathway in breast cancer." (PMID 33669698, 2021). "These biologically active factors are thought to mediate the obesity and cancer relationship by deregulating common signaling pathways, including PI3K/Akt/mTOR, a major pathway implicated in breast cancer and involved in tumor initiation, progression, growth, proliferation, invasion, and metabolism." (PMID 34426770, 2021). "If mTOR pathway activation is a mechanism by which body fatness influences breast cancer risk, the association of body fatness in relation to mTOR activation should be observed in postmenopausal women with ER+ tumors for obesity defined by high BMI, as the epidemiologic evidence indicates." (PMID 34330319, 2021). "However, the associations of WC and WHR with p-mTOR overexpressed breast cancer were similar between premenopausal and postmenopausal women." (PMID 34330319, 2021). "The presence of mutations and changes in the expression of genes related to the PI3K/Akt/mTOR pathway can constitute a useful diagnostic biomarker and may contribute to the development of new, effective and targeted breast cancer treatment methods." (PMID 33669698, 2021). "We previously reported that genetic variants in the mTOR pathway, including MTOR, were associated with increased risk of breast cancer, and there was a potential gene-environment interaction that the association for a variant was stronger in obese vs. normal-weight women." (PMID 34330319, 2021). "Interestingly, treatment of breast cancer cells with either the Akt inhibitor or the mTOR inhibitor was associated with a markedly decrease in PD-L1 cell surface expression." (PMID 35250965, 2021). "Preclinical data support that PI3K and AKT can phosphorylate ERα at Ser167 to activate ERα independently in the absence of estrogen, so the interaction between ER and PI3K/AKT/mTOR pathway hyperactivation causes breast cancer cells to lose sensitivity to endocrine therapy." (PMID 33790792, 2021). "Additionally, the long-term exposure of breast cancer cells to hypoxia resulted in the downregulation of mTOR signaling, which was associated with an increased number of dormant populations." (PMID 34832087, 2021). "Taken together, these studies provide evidence that activation of AKT-signaling is an adverse prognostic factor in breast cancer and support the rational for normalizing insulin-driven PI3K/AKT/mTOR-signaling pathway in women with breast cancer and woman at risk for breast cancer." (PMID 32153503, 2020). "However, the mTOR mutation in breast cancer resulting in mTORC1 inhibition leads to AKT activation via upregulation of receptor tyrosine kinases, leading to resistance to these inhibitors." (PMID 32782388, 2020). "Moreover, an aggressive phenotype of breast cancer that is associated with complex I mutations can be reversed via restoration of complex I function that is associated with decreased mTOR activity." (PMID 32157127, 2020). "We propose that deficiency of the lysosomal endoproteinase Ctsl in mammary cancers results in a lysosomal storage phenotype, altered amino acid levels, and interference with mTOR signaling, causing the six-week delay observed for MMTV-Cre/Ctsl−/− breast tumors." (PMID 32707827, 2020). "Finally, from IPA analysis mTOR-p70S6K signaling resulted enriched in the Top Canonical Pathways, in agreement with its frequent deregulation found in breast cancer, often associated to drug resistance." (PMID 32107391, 2020).
breast cancer (continued). "In agreement with Edu results, silencing eEF-2K caused an accumulation of cells in the G0/G1 population and a reduction in S and G2/M population in everolimus-treated breast cancer cells, indicating that suppression of eEF-2K further caused G0/G1 cell cycle arrest induced by mTOR inhibitor." (PMID 33144562, 2020). "Mutations in the PI3K/AKT/mTOR pathway are frequently detected in breast cancer." (PMID 32606352, 2020). "Aspirin use post-diagnosis may modify components of the PI3K pathway, including AKT and mTOR, and has been associated with lower risk of breast cancer recurrence and mortality." (PMID 32326897, 2020). "In conclusion, the investigation of mutations that occur in the PI3K/AKT/mTOR signaling pathway, but also of its inhibitors, may be a real benefit for patients diagnosed with breast cancer." (PMID 33375317, 2020). "Comparative transcriptomic analyses of ex vivo vs de novo CTCs identified increased mTOR signaling—a critical pathway frequently dysregulated in breast cancer and implicated in cell survival and dormancy—with contrasting actions by its two complementary arms (mTORC2/mTORC1)." (PMID 32575420, 2020). "We identified mTOR signaling, a critical pathway frequently dysregulated in breast cancer and implicated in cell survival and dormancy through its two complementary arms (mTORC1 and mTORC2), as the most significantly activated signaling pathway of ex vivo cells." (PMID 32575420, 2020). "The cultivation of breast cancer cells with AZD8055 caused the emergence of AZD8055-resistant clones that harbored increased mTOR kinase activity due to single amino acid mutations in the mTOR kinase domain that led to increased kinase activity." (PMID 31510109, 2019). "Mutations in the PIK3CA/AKT/mTOR pathway are frequent in breast cancer patients." (PMID 31088410, 2019). "In addition, we discovered that DEPDC1 caused hyper-activation of PI3K/AKT/mTOR signaling in breast cancer cells." (PMID 31032225, 2019). "Therefore, we conducted this retrospective cohort study to compare the efficacy of molecularly matched targeted therapy with everolimus to conventional therapy in refractory breast cancer patients harboring PI3K/ATK/mTOR pathway activating mutations." (PMID 31385461, 2019). "In triple negative breast cancer, PTPN13, the transcriptional target gene of SMYD2, could be phosphorylated by SMYD2 and link SMYD2 to breast cancer associated signaling pathways, such as ERK, and mTOR signaling pathways, further affected breast cancer growth." (PMID 31548876, 2019). "Therefore, we conducted this retrospective study to assess the efficacy of molecularly matched off‐label use of everolimus compared with conventional therapy in refractory breast cancer patients with active mutations in PI3K/ATK/mTOR pathway." (PMID 31385461, 2019). "Therefore, suppression of AKT activation and mTOR expression mediated the inhibitory effects of RA on breast cancer cell-associated osteolysis." (PMID 29515110, 2018). "Actionable mutations in PI3K/AKT/mTOR pathway are frequent in breast cancer brain metastases." (PMID 28993799, 2017). "However, when considered as a separate category, all 18 samples with mutations in both PIK3CA and PTEN genes (breast cancer, endometrial carcinoma, ovarian cancer and urinary bladder cancer) also displayed mTOR-pathway activation (χ2p=0.0471)." (PMID 29137436, 2017). "The mTOR/p70s6k signaling pathway is implicated in cell proliferation, invasion, and metastasis in many cancers including squamous cell carcinomas of the head and neck, hepatocellular carcinomas, breast cancer, and EC." (PMID 28487599, 2017). "Additionally, upregulation of the PI3K/Akt/mTOR pathway is associated with poor outcome for breast cancer patients and has been observed in AI-resistant breast cancer models." (PMID 27421652, 2016).
breast cancer (continued). "Interestingly, AE suppressed YB-1 expression through the downregulation of the intracellular integrin-linked kinase (ILK)/protein kinase B (Akt)/mTOR signaling pathway in HER-2-overexpressing breast cancer cells." (PMID 27391337, 2016). "Therefore, this case-control study was performed to test the association between mTOR genetic polymorphisms and breast cancer risk, as well as clinical outcomes." (PMID 27533457, 2016). "Furthermore, we analyzed the association between mTOR haplotypes and the risk of breast cancer and detected that the Crs2536Grs2295080 haplotype was associated with a significantly decreased risk of breast cancer." (PMID 27533457, 2016). "However, the previous studies were limited by their sample sizes and statistical powers, and drew no conclusions about the association between the genetic variations of mTOR and breast cancer." (PMID 27533457, 2016). "We analyzed the association between mTOR haplotypes and the risk of breast cancer." (PMID 27533457, 2016). "Activation of mTOR is implicated in the development and progression of breast cancer." (PMID 27748082, 2016). "Indeed, previous studies have demonstrated that increased PI3K-Akt-mTOR pathway activity is associated with chemoresistance in patients and in breast cancer cell lines." (PMID 27589846, 2016). "The HER2-positive tumor in LKB1−/− mice has an altered metabolic pathway, suggesting that loss of LKB1 might be an indicator of hyperactive mTOR in HER2-positive breast cancer." (PMID 26877155, 2016). "PIK3CA mutations do not have clinical validity to predict intrinsic resistance to adjuvant tamoxifen and may therefore be unsuitable as companion diagnostic for PI3K/AKT/mTOR inhibitors in ERα- positive, postmenopausal, early breast cancer patients." (PMID 24467828, 2014). "Although 17β-estradiol (E2) treatment of breast cancer cell lines induced cell proliferation in an mTOR dependent manner, the molecular mechanism underlying mTOR-mediated ERα signaling in breast cancer remains unclear." (PMID 25283550, 2014). "Moreover, another important finding in the current study was the suppression of GSK3β activity underlying the mechanism whereby Aur-A activated mTOR signaling in breast cancer cells." (PMID 25115395, 2014). "Indeed, knockdown of mTOR expression by mTOR-siRNA caused a significant inhibition of breast cancer cell viability and a notable increase in cell apoptosis vs. the control group, in a manner similar to those transfected with miR-99a mimics." (PMID 24637915, 2014). "We hypothesized that FASN may be the downstream effector underlying ER/HER2 crosstalk through the PI3K/AKT/mTOR pathway in ER/HER2-positive breast cancer." (PMID 24866893, 2014). "These and other positive results suggest mTOR inhibitors may prove to be particularly useful cancer prevention agents in women at high-risk of breast cancer." (PMID 24069582, 2013). "PI3K/AKT/mTOR pathway activation has been implicated in endocrine resistance in breast cancer." (PMID 23844554, 2013). "To assess whether the loss of LKB1 leads to mTOR-dependent glucose addiction in breast cancer, we analyzed the glycolytic profile of NIC tumor cells in response to glucose availability." (PMID 24280377, 2013). "However, p4E-BP1 was also chosen because it has been shown to be a hallmark protein downstream of mTOR that is associated with grade and survival in ovarian cancer as well as in breast cancer." (PMID 19240722, 2009). "mTOR signaling is often overactive in multiple cancer types including breast cancer and mTOR antagonist are employed in clinical studies for BC, especially in association with cytotoxic chemotherapy." (PMID 36835056, 2023). "Therefore, studying genetic polymorphisms in the mTOR pathway may shed light on connections between obesity and breast cancer risk." (PMID 36831624, 2023).
breast cancer (continued). "In addition to these cancer-specific gene sets, the F1 and F2 populations were also significantly enriched for TNFα, MAPK, IL-1 7, ErbB, HIF- 1, RAS, RAP 1, PI3K-AKT, and mTOR signaling pathways, all of which have previously associated with breast cancer metastasis." (PMID 35614362, 2022). "In addition, OSGIN1 also regulates the autophagy process by enhancing autophagosome formation in ROS-dependent pathways, which are associated with the activation of the AMPK/mTOR signaling pathway after docosahexaenoic acid (DHA) treatment in breast cancer cells." (PMID 35625730, 2022). "Furthermore, activation of the phosphatidylinositol-3-kinase (PI3K)/AKT/mechanistic target of rapamycin (mTOR) pathway in ERα-positive breast cancers has been associated with relapse and death in patients treated with tamoxifen, supporting in vitro evidence that AKT mediates tamoxifen resistance." (PMID 35441158, 2022). "Thus, our findings suggest that mechanisms other than mTOR may explain the inverse association between BMI and ER– breast cancer." (PMID 34330319, 2021). "The activated mTOR protein promotes substrate phosphorylation and gene transcription, activates the non‐ligand‐dependent transcription activation function 1 (AF‐1), induces phosphorylation of ERα and promotes proliferation and invasion of breast cancer cells, causing endocrine therapy resistance." (PMID 34651424, 2021). "Our findings suggest that metabolic plasticity (high mTOR activity and the overexpression of at least two alternative metabolic pathway–related enzymes) could be a subtype-independent risk factor in breast cancers, certain lung tumors rhabdomyosarcomas, and pheochromocytomas." (PMID 35029792, 2021). "Therefore, blocking PI3K/AKT/mTOR and the cell cycle pathway may be helpful for risk score-high breast cancer patients, and the subsequent drug-sensitive analysis targeted to these pathways confirmed this." (PMID 34953500, 2021). "Finally, mutations in mTOR were found in 1.8% of breast cancer." (PMID 32605126, 2020). "This makes the PI3K/Akt/mTOR pathway a crucial object of study for understanding the development and progression of this disease, the role of this pathway as a potential therapeutic target, and the prognostic and diagnostic value of this pathway in patients with breast cancer." (PMID 32211045, 2020). "However, studies conducted on MCF-7 and MDA-MB-231 breast cancer lines showed that MEL inhibits the PI3K/Akt/mTOR signaling pathway that may cause autophagy induction." (PMID 31878020, 2019). "Therefore, the identification and classification of PI3K/AKT/mTOR signaling pathway activation is closely related to the breast cancer subtypes, because it is susceptible to potential drug interventions, which selectively target tumors while leaving normal tissue alive." (PMID 29614812, 2018). "Furthermore, SLC6A14 enhances the growth of ER-positive breast cancer in spontaneous mouse models of breast cancer; this mechanism may be associated with mTOR signaling." (PMID 29562706, 2018). "Furthermore, metformin elicited less rebound upregulation of total proteins in the mTOR pathway (namely, P70 S6K) in breast cancer cells, which potentially imposes a lesser risk of emergence of drug resistance to mTOR inhibition in breast cancer treatment regimens." (PMID 27748082, 2016). "Therefore, mTOR rs2295080 polymorphism might play a critical role on predicting the prognosis of patients with breast cancer." (PMID 27533457, 2016). "Inhibition of mTOR with rapalogs has shown clinical efficacy against some solid tumors, including everolimus for angiomyolipoma associated with tuberous sclerosis, metastatic renal cell carcinoma, breast cancer, or pancreatic neuroendocrine carcinomas and temsirolimus for renal cell carcinoma." (PMID 24777052, 2014).
breast cancer (continued). "In addition, high mTOR expression was associated with a poor prognosis in several human cancers, including renal cell cancer, lung cancer, breast cancer, laryngeal squamous cell carcinoma, neuroendocrine tumors, biliary tract adenocarcinoma, and colorectal cancers." (PMID 24816861, 2014). "Among the most targeted of these is the PI3K/Akt/mTOR axis, a central conduit of mitogenic signaling that is frequently hyperactivated in breast cancer." (PMID 41496977, 2026). "The PI3K/AKT/mTOR signaling cascade represents a critical indication of endocrine resistance and tumor progression in this subtype of breast cancer." (PMID 42194764, 2026). "Alpelisib, targeting the PI3Kα isoform, provides meaningful benefit in PIK3CA-mutated breast cancer and represents a promising strategy in gynecologic tumors with aberrant PI3K/AKT/mTOR pathway activation." (PMID 42194689, 2026). "Combining with endocrine therapy, PI3K inhibitors alpelisib, AKT inhibitors capivasertib, and mTOR inhibitors everolimus have been applied clinically in breast cancer treatment, especially in hormone receptor (+)/HER2(−) subtypes, to overcome resistance." (PMID 41510186, 2026). "PI3K/AKT/mTOR inhibitors targeting this pathway have a positive impact on strengthening the treatment and improving the prognosis of breast cancer patients." (PMID 41510186, 2026). "Although the mammalian target of rapamycin (mTOR) inhibitor everolimus and the cyclin‐dependent kinase 4/6 inhibitor palbociclib have been used to prevent endocrine resistance in breast cancer, these drugs also have some side effects." (PMID 41513589, 2026). "In this study, we synthesized novel 2-aryl-6-carboxamide-substituted benzoxazole derivatives and evaluated their anticancer potential against breast cancer cell lines, with a focus on mTOR inhibitory activity." (PMID 42294223, 2026). "In this study, we elucidated that YTHDF3 regulates the glycolysis level, proliferation and migration of breast cancer through the mTOR-HIF1α-LDHA axis." (PMID 42036761, 2026). "Dysregulation of the PI3K/AKT/mTOR pathway is among the most frequent molecular alterations in breast cancer and plays a central role in resistance to both endocrine therapy and CDK4/6 inhibition." (PMID 41510186, 2026). "Overall, COH-17 and COH-19 demonstrated potent anticancer effects through mTOR inhibition, induction of apoptosis, and cell cycle arrest, highlighting their potential as targeted therapeutic agents for breast cancer." (PMID 42294223, 2026). "Everolimus, an mTOR (mammalian target of rapamycin) inhibitor, is one of the treatment options for HR-positive advanced/recurrent breast cancer, but it is known for its high incidence of DILD (3–33%), however its prognosis is relatively good." (PMID 41417148, 2026). "Mechanistically, YTHDF3 enhances the expression of HIF1α and LDHA and glycolysis by inducing the phosphorylation of mTOR, and finally promotes the occurrence and development of breast cancer." (PMID 42036761, 2026). "mTOR inhibitors have shown promise in preclinical studies for treating breast cancer and renal cell carcinoma by targeting metabolic pathways that promote resistance." (PMID 40051496, 2025). "The pathway analyses suggested genes involved in multiple cancer‐related pathways, such as “gastric cancer,” “mTOR signaling pathway,” and “breast cancer,” had methylation profiles related to both folate and toxicities." (PMID 40420697, 2025). "Dual PI3K/mTOR inhibitors have shown remarkable radiosensitizing effects across different breast cancer subtypes." (PMID 40725100, 2025). "This study concluded that IVM with MET activated autophagy, which killed breast cancer cells by inhibiting the activation of the PI3K/AKT/mTOR pathway and promoting the excessive accumulation of ROS." (PMID 40699802, 2025). "According to these results, ADPE inhibits the AKT/mTOR signaling pathway, which is important for controlling the development and division of breast cancer cells." (PMID 40717210, 2025).